SOD1 (superoxide dismutase 1)
Diseases named in the same sentence as SOD1 in open-access papers (continued):
Sharing a sentence is not in itself a finding about the gene and the disease.
cancer (continued). "CPT-induced SOD1 acetylation was stimulated by its provoked ROS, suggesting a positive feedback loop, in which ROS per se impairs the antioxidative defence of cancer cells and reinforces oxidative stress stimulated by anticancer agents." (PMID 26008972, 2015). "In this study, we have provided the first evidence showing that genotoxic agents caused ROS accumulation was able to impair the antioxidant capacity of cancer cells via diminishing the activity of antioxidant enzyme SOD1." (PMID 26008972, 2015). "The current study provides the first evidence that the dun1 sod1 SL interaction first identified in yeast, is evolutionarily conserved in a human cancer context." (PMID 26318585, 2015). "Alterations in both SOD1 and CAT have been implicated in cancer, most likely due to their roles in modulating ROS levels." (PMID 26569310, 2015). "This study started from the validation of occurrence of SOD1 acetylation in cancer cells, and focused on the investigation of the biological significance of SOD1 acetylation." (PMID 26008972, 2015). "We firstly validated the acetylation of SOD1 using a pan-specific anti-acetylated lysine antibody in cancer cells with ectopically expressed SOD1." (PMID 26008972, 2015). "According to our results, the basal level of SOD1 acetylation varies largely among either the cancer cell lines or patients tumor tissues; high level SOD1 acetylation is closely correlated with the increased response to CPT treatment." (PMID 26008972, 2015). "This review summarizes the studies reporting important roles of SOD1 in cancer and addresses the potential cross-talk between the overexpression of SOD1 and the regulation of the mitochondrial unfolded protein response (UPRmt)." (PMID 24955214, 2014). "TM is known to decrease angiogenesis and cancer cell growth through the inhibition of cellular antioxidant copper zinc superoxide dismutase (SOD1) and to elevate levels of cellular reactive oxygen species (ROS)." (PMID 22502731, 2012). "SOD1 is a key antioxidant enzyme with known oncogenic roles in several human cancers." (PMID 40867576, 2025). "It promotes tumor cell proliferation, survival, and metastasis by regulating ROS levels in cancer, and as a novel target, the inhibition of SOD1 expression may be effective in slowing down cancer progression." (PMID 40299448, 2025). "Alterations in SOD1 expression have also been found in various cancers." (PMID 38483584, 2024). "Ongoing efforts are underway to develop SOD1 inhibitors for the treatment of cancer and ALS, and it is conceivable these may be useful in the context of PPM1D mutation." (PMID 38896450, 2024). "Also, SOD1 has been proposed as a novel target for anticancer therapy since it remains overexpressed in a number of cancers along with increased ROS levels in order to prevent any damage caused due to excessive ROS and maintain tumorigenesis." (PMID 38400579, 2024). "Notably, disulfiram derivatives, such as DDC, have been found to inhibit Superoxide Dismutase 1 (SOD1), a protein associated with cancer cell survival and a current drawback in cancer treatment strategies." (PMID 39034442, 2024). "Increased expression of SOD1 is usually correlated with disease progression in these cancers." (PMID 38483584, 2024). "Overexpression of SOD1 in PAAD protects cancer cells from oxidative stress." (PMID 37822927, 2023). "Emerging evidence from several groups now indicates that SOD1 is overexpressed in cancers, and the activity of SOD1 may be essential to maintaining cellular ROS below a critical threshold." (PMID 38726050, 2023). "Additionally, while NQO1:CAT was not directly measured, inhibition of catalase and GSH did not lead to sensitization of KEAP1-mutated NSCLC during β-lapachone treatment, while inhibition of TXNRD and SOD1 sensitized cancers." (PMID 36978989, 2023). "Several groups have identified SOD1 as a potential therapeutic target in cancer." (PMID 37215572, 2023).
cancer (continued). "Notably, mammalian SOD1 has been explored as a cancer therapeutic target for the selective killing of cancer cells with defective HR genes, such as BLM or RAD54B." (PMID 37638880, 2023). "Therefore, it was believed that the increase in CRC grade was proportional to the increase in the production of SOD1 as a human anti-cancer antioxidant." (PMID 37759978, 2023). "In terms of cancer diagnosis, the SOD1 level might be used as a valuable biomarker for the detection of human colon cancer." (PMID 37759978, 2023). "Furthermore, tetrandrine contributes to the suppression of EMT and cancer stemness in MDA-MB-231 cells by disrupting superoxide dismutase 1 (SOD1) signaling and increasing reactive oxygen species (ROS) production." (PMID 37570775, 2023). "Alterations in the proteins that are usually associated with cancer, including the upregulation of peroxiredoxin-1, annexin 5, and iNOS, and down-regulation of RDH12, retinaldehyde dehydrogenase 1, SOD1, and MYL 9, were found in the EC tissues of the diabetic group." (PMID 35454982, 2022). "Cancer-associated protein alterations such as upregulation of peroxiredoxin-1, annexin 5, and iNOS, and downregulation of RDH12, retinaldehyde dehydrogenase 1, SOD1, and MYL 9, were found in the EC tissues of the diabetic group." (PMID 35454982, 2022). "Moreover, we found that the specific inhibition of SOD1 in cancer and normal cells represses the signaling pathways and their crosstalk that supports cancer cell growth but stimulates the signaling network that promotes cancer cell cycle arrest and apoptosis." (PMID 36293533, 2022). "Considering the pivot role of SOD1 in the balance of anti‐/pro‐oxidative system, the inactivation of SOD1 is considered to be an important pathogenesis of many diseases such as cardiovascular disease, aging, and cancer." (PMID 34986524, 2022). "On the other hand, a decreased level of SOD1 by Cur-D could be explained by its toxic nature, as Cur-D shows toxicity to many cells, especially to cancer cells." (PMID 34072078, 2021). "In conclusion, the present study uncovered a new mechanism for the herbal compound OA to impair cancer cell growth by blocking the PSP via the degradation of key metabolic enzymes in this pathway through the SOD1/ROS/AMPK/mTORC1/macroautophagy/lysosome pathway." (PMID 34703880, 2021). "Recently, emerging evidence from researchers has indicated that SOD1 is usually overexpressed in cancer cells; its activity is essential to maintain higher ROS levels under the critical threshold during aberrant energy metabolism of cancer progression." (PMID 35011380, 2021). "Therefore, SOD1 inhibition by ATN-224 results in the down-regulation of multiple signaling pathways for cancer cell function, such as ERK1/2 and anti-apoptotic factor Mcl1." (PMID 35011380, 2021). "During SOD1 inhibition in cancer cells, LD100 could repress the ERK, PI3K-Akt, and NF-κB pathways; arrest the cell cycle; and induce mitochondria-dependent apoptosis." (PMID 35011380, 2021). "Previous studies revealed superoxide dismutase (an antioxidant) activity facilitated anoikis resistance in ECM detached cancer cells, so we sought to investigate the effect of metformin treatment on two antioxidant families glutathione peroxidase 1–3 and superoxide dismutase 1–3." (PMID 35054435, 2021). "In addition, CXCL1 secreted from CAFs was found to cause the accumulation of reactive oxygen species (ROS) in irradiated cancer cells by inhibiting the ROS-scavenging enzyme superoxide dismutase 1 (SOD1), leading to enhanced DNA damage repair in cancer cells." (PMID 34135469, 2021). "However, the use of inorganic strategies to develop anti-cancer drugs based on SOD1 inhibition still requires further efforts." (PMID 35011380, 2021). "In summary, LD100 may be the most effective SOD1 inhibitor so far and has application prospects for cancer treatment." (PMID 35011380, 2021).
cancer (continued). "Moreover, OA suppressed PSP of cancer cells via activating the SOD1/ROS/AMPK/mTORC1/macroautophagy/lysosomal pathway." (PMID 34703880, 2021). "Redox homeostasis in cancer cells is aberrant and its regulation may be under the control of the cell antioxidant defense based on SOD1, CAT, and the glutathione system." (PMID 33924212, 2021). "Growing evidence suggests that SOD1 plays important role in cancer, particularly KRAS-driven NSCLC." (PMID 33859191, 2021). "Superoxide dismutase 1(SOD1) is a major antioxidant with oncogenic effects in many human cancers." (PMID 32391354, 2020). "In addition, we found that mass pan-cancer SOD1 expression levels differed from those in normal tissues, also the SOD1 expression levels varied in different normal tissues." (PMID 32391354, 2020). "SOD1 level can be used as a valuable biomarker to detect cancer in the human colon." (PMID 32994983, 2020). "We hypothesized that deletion of Sod1 would exacerbate cancer cachexia when compared with wild‐type (WT) counterparts." (PMID 32918528, 2020). "Consequently, ATN-224-treated cancer cells enter programmed caspase-mediated apoptosis in vitro and in vivo suggesting SOD1 as a tumor promoter and a potential novel target for cancer therapy." (PMID 29478325, 2019). "SOD1 has a diverse effect on cancer cell signal transduction, growth, and survival." (PMID 29478325, 2019). "Therefore, the specific SOD1 inhibition selectively represses the signaling pathways to sustain uncontrollable growth of cancer cells and stimulates the pathways to promote cancer cell cycle arrest." (PMID 30911355, 2019). "Therefore, SOD1 supports cancer cell growth by maintaining proliferative signal transduction, protecting cells from ROS-derived induction of apoptosis and inducing the metabolic switch from normal respiration to aerobic glycolysis." (PMID 29478325, 2019). "EIF4G2 and PABPC1 may be involved in the progression of cancer by affecting translational initiation, while SOD1 and ATP5H may participate in carcinogenesis via influencing oxidative stress and oxidative phosphorylation." (PMID 30863671, 2019). "In parallel, SOD1 (superoxide dismutase 1 Cu-Zn) expression was studied because previous studies in other cancer types had suggested that redox state of tumor cells could be involved in 64Cu-ATSM uptake." (PMID 31858290, 2019). "For this reason, SOD1 must maintain the viability of cancer cells." (PMID 29891006, 2018). "This makes SOD1 a potential target for anti-cancer therapies, and its inhibitors may find application in anticancer therapy." (PMID 30347787, 2018). "SOD1 overexpression is frequently observed in many cancers, whereas SOD2 is downregulated." (PMID 30279365, 2018). "This is important in the context of effective anticancer therapy, since many cancer cells have been shown to overexpress SOD1, which may impair the action of DOX." (PMID 30347787, 2018). "Furthermore, SOD1 has been identified as a novel cancer drug target, suggesting that SOD1 inhibition impairs cancer." (PMID 29360852, 2018). "Blocking the route of copper to SOD1 through hCCS has been shown to inhibit cancer proliferation." (PMID 27282955, 2016). "In most cases, the shorter lifespan of Sod1−/− mice may be directly attributed to an increase in cancer rate, particularly of a rare (for C57BL/6 mice) cancer, hepatocellular carcinoma." (PMID 27438860, 2016). "We note that inhibiting the direct interaction of SOD1 with its chaperone may indeed be the contributory factor in the success of cisplatin as a cancer therapeutic." (PMID 27282955, 2016). "Thus abundant basal level of SOD1 acetylation is able to stratify the subset with low capacity to copy with oxidative stress of cancer cells." (PMID 26008972, 2015). "In order to understand the relation between NF-κB inactivation and PDTC pro-oxidant effects, we examined whether SOD1 could be one of the target gene of PDTC treatment in hematopoietic human cancer cell line U937." (PMID 25996379, 2015).
cancer (continued). "One possible explanation is that most cancer cells feature a high antioxidant capacity, in which SOD1, as a critical anti-oxidant enzyme, may maintain a high basal activity and can hardly to be further enhanced." (PMID 26008972, 2015). "CPT treatment increased ROS generation in cancer cells whilst suppressed SOD1 activity." (PMID 26008972, 2015). "We speculate that while cancer cells often feature an increased antioxidant capacity, high level of SOD1 acetylation represents an intrinsic silencing of SOD1, and is also an indicator of low activity of SIRT1." (PMID 26008972, 2015). "Overexpression of SOD1 in cancer cells may act as adaptation mechanism to maintain total ROS levels below a critical threshold so that the integrity of the organelle is maintained." (PMID 25996379, 2015). "Together, these data provided the first evidence showing that chemotherapies induce SOD1 acetylation and impair its enzymatic activity in cancer cells, which may result from disrupted interaction with SIRT1." (PMID 26008972, 2015). "SOD1 is essential for maintaining the redox homeostasis of cancer cells." (PMID 26008972, 2015). "Therefore, we aimed to evaluate the effect of PDTC on the human Cu/Zn superoxide dismutase 1 (SOD1) gene transcription in hematopoietic human cancer cell line U937." (PMID 25996379, 2015). "While the contribution of SOD1 in the cytoplasm is undeniable, we propose the IMS-fraction of SOD1 may also play an important role in maintaining the viability of cancer cells and that SOD1 may potentially become a therapeutic target for cancer." (PMID 24955214, 2014). "Collectively, these dismutase-dependent and independent roles of SOD1 may explain the apparent addiction of cancer cells to this enzyme." (PMID 24955214, 2014). "SOD1 is rapidly emerging as a novel target for cancer therapy." (PMID 24955214, 2014). "This review focuses on an emerging role of SOD1 in cancer biology, where as in ALS, we propose that the IMS-fraction may be of significant importance by playing dismutase-dependent and independent roles." (PMID 24955214, 2014). "How inhibition of SOD1 leads to cancer cell death and whether inhibition of the IMS-fraction of SOD1 contributes to the effect of LCS-1 was not addressed." (PMID 24955214, 2014). "A recent study by the Chandel's group further supports the notion of SOD1 as a target in cancer." (PMID 24955214, 2014). "Emerging evidences from several groups now indicate that SOD1 is overexpressed in cancers and that the activity of SOD1 may be essential to maintain cellular ROS under this critical threshold." (PMID 24955214, 2014). "Our findings suggest that SOD-1, which is localised mainly in the cytoplasm of cancer cells, may protect cells from cytotoxic insult." (PMID 22394685, 2012). "Together, these findings establish SOD enzymes as key redox regulators in cancer biology: their overexpression supports tumor adaptation under oxidative stress, while their inhibition reveals critical vulnerabilities—particularly in the case of SOD1—that may be therapeutically exploitable." (PMID 40867898, 2025). "One aspect limiting the application of a SOD1 inhibitor in cancer could be toxicity." (PMID 39187509, 2024). "Consequently, SOD1 is often overproduced in various types of cancers." (PMID 39330521, 2024). "Concerning SOD1, measuring its levels in the blood could provide insights into the oxidative stress status of cancer cells, making this protein a possible biomarker for cancer diagnosis and monitoring." (PMID 39123408, 2024). "Indeed, cancer cells upregulate several Cu2+ chaperones such as the copper chaperone for SOD1 (CCS), which binds cytosolic Cu2+ and transfers it to SOD1, and pharmacological disruption of this process can have therapeutic effects on cancer as it reduces uncontrolled cell proliferation." (PMID 37132605, 2024). "Therefore, SOD1 is a potential target for anti-cancer therapies, and its inhibitors may find application in anticancer therapy." (PMID 36985725, 2023).
cancer (continued). "Moreover, accumulating evidence have shown that the expression of SOD1 is significantly up-regulated in many types of malignant tumors, which may lead to the deterioration of the disease and poor prognosis by regulating cell proliferation and oxidative stress." (PMID 37223030, 2023). "Therefore, additional studies about SOD1 in cancer and ferroptosis are needed to establish its role and whether it might be used as a pan-cancer targetable dependency." (PMID 35912247, 2022). "However, the role of SOD1 in cancer is not fully understood." (PMID 33859191, 2021). "In addition, SOD1 was also differentially expressed in pan-cancer and normal tissues, indicating that it is tissue-specific and may play different or even opposite roles in different types of cancer." (PMID 32391354, 2020). "Moreover, altered expression of proteins (NDUFS1, SOD1, SERPINA5, and UQCRC2) involved in sperm fertility potential and motility suggests that the fertility of cancer patients may be at risk due to the aberrant expression of critical sperm proteins." (PMID 32942548, 2020). "However, whether SOD1 acts as a master regulator of ROS signaling pathways in cancer biology remains elusive." (PMID 30911355, 2019). "Therefore, the modulation in the ratio of SOD1/SOD2 may be a promising strategy for treating cancer cells." (PMID 30279365, 2018). "However, SOD levels also increase with tumor progression in these and other cancers, with similar changes occurring in other antioxidants, such as cytoplasmic SOD1 and catalase." (PMID 28744456, 2017). "Thus, it is possible that Sod1−/− mice reach a “theoretical threshold limit of oxidative damage” required to accelerate the aging process as a whole, or perhaps to drive the increase in cancer rate, that is unmet in other antioxidant mutant mouse models." (PMID 27438860, 2016). "Finally, the data presented here support the hypothesis that SOD1 is a potential therapeutic target for the treatment of cancer and that inhibiting SOD1 results in the down-regulation of multiple signaling pathways important for tumor cell function." (PMID 25996379, 2015). "In addition to fALS, the importance of SOD1 is beginning to emerge as critical in cancer biology." (PMID 24955214, 2014). "Overexpression of SOD1 and SOD3 in cancers helps to maintain cellular ROS under the critical threshold, and improve response to chemotherapy, respectively." (PMID 40426890, 2025). "Specifically, SOD1 facilitates the dismutation of O2− into H2O2, a stable ROS messenger that is pivotal for regulating oxidative stress and supporting oncogene-driven cancer cell proliferation." (PMID 38535948, 2024). "In summary, our results highlight the potential of targeting SOD1 expression, either through DDC or siRNA‐based suppression, to significantly enhance the effectiveness of SF in inducing cancer cell death." (PMID 39034442, 2024). "In cancer, hydrogen peroxide (H2O2) is a well-studied signaling molecule produced by the enzymatic action of superoxide dismutases 1, 2, and 3 (SOD1, 2, and 3) situated in the cytosol, mitochondrial matrix, and extracellular space, respectively." (PMID 38247453, 2023). "Mice deficient in some of the most relevant antioxidant enzymes, such as the superoxide dismutase (SOD) family (in particular the cytoplasmic SOD1 and the mitochondrial SOD2), as well as peroxiredoxin 1, developed different cancers spontaneously." (PMID 37627552, 2023). "Studies of SOD1, SOD2, or SOD3 in colorectal, lung, and other cancers have also been widely reported." (PMID 37759978, 2023). "MRP1 is primarily involved in drug efflux in various cancer cells whereas NQO1 and SOD1 upregulation increases drug resistance making the prognosis even worse." (PMID 37305533, 2023).